LINC01614 (long independently transcribed non-coding RNA 1614)
Diseases named in the same sentence as LINC01614 in open-access papers (continued):
Sharing a sentence is not in itself a finding about the gene and the disease.
cancer (16 papers, 2018 to 2025). A tumor composed of atypical neoplastic, often pleomorphic cells that invade other tissues. "According to previous studies, LINC01614 has been implicated as an oncogene, exerting regulatory control over various cellular processes in different cancer types." (PMID 40735832, 2025). "LINC01614 located in the cytoplasm can function as a cytoplasmic lncRNA, and its upregulation can cause poor prognosis in various cancers." (PMID 38655053, 2024). "We explored the relationship among 42 RNA methylation-related genes associated with m6A, m5C, and mlA processes and found that LINC01614 expression was associated with most RNA-regulating genes in almost 26 cancers." (PMID 38655053, 2024). "Although studies still need further investigation, these results suggested that LINC01614 could function as a cytoplasmic lncRNA in various cancers, and its upregulation could cause poor prognosis." (PMID 38655053, 2024). "LINC01614 dysregulation is associated with cancer development." (PMID 39282156, 2023). "TIP analysis demonstrated LINC01614 closely associated with cancer-immunity cycle in PTC." (PMID 34604079, 2021). "Our study provides novel insights into the role of LINC01614 in cancer and may aid in the development of diagnostic and therapeutic tools for LUAD treatment." (PMID 29934982, 2018). "The diverse roles of LINC01614 in different cancers underscore its potential as a key regulatory molecule in tumourigenesis." (PMID 40735832, 2025). "As such, further studies are warranted to explore the full spectrum of LINC01614's interactions with miRNAs in other cancers and to assess its potential as a therapeutic target for cancer treatment." (PMID 40735832, 2025). "The interaction of LINC01614 with miR-138-5p was subsequently detected by dual-luciferase reporter assays, which confirmed that miR-138-5p exerts a cancer-suppressive effect in various cancers." (PMID 39596660, 2024). "In this study, we found that 23 out of 30 cancers showed a significant abnormal expression of LINC01614." (PMID 38655053, 2024). "Univariate Cox regression results assessing the prognostic value of LINC01614 expression levels indicated that high levels of LINC01614 predict short overall survival (OS) for 21 cancer types and predict long OS only for DLBC patients." (PMID 38655053, 2024). "Our findings indicate significant variability in LINC01614 expression among the molecular subtypes of seven cancers, namely, COAD, ESCA, HNSC, KIRP, LGG, LUSC, and STAD." (PMID 38655053, 2024). "In this study, LINC01614 expression was positively correlated with regulatory genes of RNA methylation for several cancers." (PMID 38655053, 2024). "Recently, a long non-coding RNA (lncRNA), LINC01614, has emerged as a vital gene regulator in cancer progression." (PMID 39282156, 2023). "First, we analyzed LINC01614 expression in 41 pairs of cancer and normal tissues in the TCGA database and found that LINC01614 was upregulated in cancer tissues." (PMID 39282156, 2023). "We found that LINC01614 expression was significantly (P < 0.01) upregulated in CRC cell lines, a result that was in line with LINC01614 expression in cancer tissues." (PMID 39282156, 2023). "In the pan-cancer analysis, we found that FOXD2-AS1 and LINC01614 were highly expressed in most cancer types." (PMID 34604079, 2021). "Moreover, the interaction of LINC01614 with miR‐138‐5p has been observed to suppress cancer‐suppressive effects in other malignancies." (PMID 40735832, 2025). "In addition, we have conducted an examination of LINC01614 expression patterns across different molecular subtypes in a variety of cancers." (PMID 38655053, 2024). "Although the mechanism of LINC01614 influence on cancer stemness remains not fully understood, our study indicated that LINC01614 could widely affect the stemness of different tumors." (PMID 38655053, 2024). "Several reports have confirmed the role of LINC01614 in cancer." (PMID 39596660, 2024).
cancer (continued). "Furthermore, Linc01614 was also found significantly positively co-expressed with PODNL1 in multiple types of cancers." (PMID 37504302, 2023). "However, silencing LINC01614 in CAFs before co-injection or exosome extraction attenuated the number of metastatic cancer cells and CAFs." (PMID 36209111, 2022). "Since LINC01614 has a potential cancer-promoting effect in various cancers, including HNSC, and the biological function and oncogenic role of LINC01614 in HNSC were then tested in vivo in HNSC cell lines." (PMID 38655053, 2024). "In the LUAD, LINC01614 formed a trimeric complex with ANXA2 and p65 to facilitate the latter two molecules’ interaction and the activation of NF-κB, eventually elevating cancer cell growth." (PMID 38688909, 2024). "High levels of LINC01614 also predict poor DSS for 16 cancer types, poor DFI for 10 cancers, and poor PFI for 18 cancers, whereas for DFI of BLCA and UCEC patients or for PFI of DLBC patients, LINC01614 played a protective role." (PMID 38655053, 2024). "In our research, a few of the DEirlncRNAs in the model have already been revealed to play roles in various cancers, such as HAGLROS, LBX2-AS1, LINC00900, LINC01614, AC090673.1, and especially TC, while others were found to be related to TC for the first time." (PMID 35996170, 2022). "LINC01614, CTD-2547G23.4, LINC01355, MALAT1, CTD-2349P21.9 and RP11-468E2.10 were over-expressed, whereas RP11-672A2.4 was under-expressed in cancers." (PMID 29303984, 2018). "For instance, LINC01614 upregulated FOXP1 by binding miR-217 and promoted LUAD cancer development." (PMID 38655053, 2024). "Furthermore, the pro-inflammatory factors secreted by cancer cells, such as IL-6 and CXCL10, can upregulate the expression of LINC01614 through a feedforward loop." (PMID 37784082, 2023). "Mechanistically, LINC01614 directly interacts with ANXA2 and p65 to facilitate the activation of NF-κB, which leads to the upregulation of the glutamine transporters SLC38A2 and SLC7A5 and eventually enhances the glutamine influx of cancer cells." (PMID 36209111, 2022). "We identified LINC01614 as a CAF-specific lncRNA and demonstrated that CAF-exosome-packaged LINC01614 could regulate the glutamine metabolism of cancer cells." (PMID 36209111, 2022). "Our study demonstrated that targeting CAF-specific LINC01614 inhibits glutamine uptake and the progression of LUAD cells, highlighting that CAF-specific lncRNAs could serve as an attractive target in cancer treatment." (PMID 36209111, 2022). "Despite the significant upregulation of LINC01614 characterized here in GC along with previous reports in other cancers, the molecular mechanisms still are not clearly seen, and more explorations are also necessary to detect upstream or downstream effectors of LINC01614 in GC progression." (PMID 34691143, 2021). "Interestingly, A549 cells failed to upregulate LINC01614 expression in CAFs when silencing LINC01614 or inhibiting CAF exosome secretion, suggesting the transmission of LINC01614 from CAFs to cancer cells may form regulatory positive feedforward loops for LINC01614 upregulation in CAFs." (PMID 36209111, 2022).
LINC01614 also shares sentences with these, for which no sentence is quoted: lung squamous cell carcinoma (1 paper); uterine corpus endometrial carcinoma (1).